FAP (fibroblast activation protein alpha)
Diseases named in the same sentence as FAP in open-access papers (continued):
Sharing a sentence is not in itself a finding about the gene and the disease.
coronary artery disease (7 papers, 2013 to 2025). "Moreover, they found a higher risk of death in coronary artery disease patients with lower plasma FAP concentrations." (PMID 38297310, 2024). "Additionally, the potential role of FAP in coronary disease is exemplified by the results of studies using FAP radiotracers with PET and SPECT imaging." (PMID 40278373, 2025). "Therefore, for ischemic heart disease, a typical cardiovascular disease, we considered FAP‐targeted modulation as a strategy for CAR‐T‐cell therapy for myocardial tissue fibrosis after myocardial infarction." (PMID 39087342, 2024). "Ongoing attempts with immune-based therapeutic interventions targeting FAP in areas of active tissue remodeling suggest that specific interventions aiming at subpopulations of VSMCs expressing FAP in coronary disease may be useful in the future, and experimental models are currently being developed." (PMID 40278373, 2025). "Patients with coronary heart disease (CHD), stroke or peripheral vascular disease (PVD) also have to be excluded since expression of FAP was detected in atherosclerotic vessels." (PMID 23937772, 2013). "By targeting FAP, CAR‐T cells can be used in the clinical treatment of myocardial fibrosis in patients with ischemic heart disease and improve ventricular remodelling, which will undoubtedly provide more comprehensive understanding and strategies for the treatment of cardiovascular diseases." (PMID 39087342, 2024).
soft tissue sarcoma (7 papers, 2016 to 2026). A malignant neoplasm arising from muscle tissue, adipose tissue, blood vessels, fibrous tissue, or other supportive tissues excluding the bones. "FAP is overexpressed in cancer-associated fibroblasts (CAFs) in the stroma of more than 90% of epithelial carcinomas and many subtypes of soft tissue sarcomas (e.g., fibrosarcoma, malignant fibrous histiocytoma, and liposarcoma)." (PMID 37761371, 2023).
triple-negative breast carcinoma (7 papers, 2016 to 2026). An invasive breast carcinoma which is negative for expression of estrogen receptor (ER), progesterone receptor (PR), and human epidermal growth factor receptor 2 (HER2). "We also provided a preliminary proof of targeting efficiency in a syngeneic mouse model of triple negative breast cancer (TNBC) treated with functionalized HFn-FAP." (PMID 33562504, 2021). "Finally, we showed that HFn-FAP is able to reach the tumor and to target CAFs in a mouse syngeneic model of triple negative breast cancer after intravenous administration." (PMID 33562504, 2021). "In an orthotopic mouse model of triple-negative breast cancer (TNBC) composed of patient derived-CAFs and tumor cells, we demonstrate the efficacy of our engineered FAP UCAR T-cells in CAF depletion, reduction of desmoplasia and successful tumor infiltration." (PMID 37251405, 2023). "Indeed, we have shown that the triple-negative breast cancer cells MDA-MB-231 reduced the level of DCN and increased the level of α-SMA and FAP-α in normal breast fibroblasts in a paracrine manner." (PMID 38667295, 2024). "8/15 and 7/11 tumors in human clusters 1 and 2 respectively expressed CAF markers FAP/CSPG4, which may suggest a propensity for some lung squamous and triple-negative breast cancers (TNBC) to retain patient stroma." (PMID 26980748, 2016).
autoimmune disease (6 papers, 2021 to 2026). A disorder resulting from loss of function or tissue destruction of an organ or multiple organs, arising from humoral or cellular immune responses of the individual to their own tissue constituents. "Recent studies have revealed that FAP is also highly expressed in certain Autoimmune Diseases (AIDs) characterized by chronic inflammation and tissue remodeling." (PMID 41859079, 2026). "It is currently unknown whether depleting FAP affects TLS formation in tumours but a murine model of autoimmune disease demonstrated that genetic depletion of FAP abolishes TLS formation." (PMID 35479076, 2022). "As an imaging biomarker, FAP is also upregulated in actively remodeling tissues; therefore, the distinction between GBM and other neurological inflammatory or autoimmune diseases relies on clinical manifestations and multimodal imaging, including MRI." (PMID 34068501, 2021). "The main issue is represented by the increased FAP expression in non-cancer entities such as fibrosis and autoimmune diseases, which leads to false positive interpretations." (PMID 38398230, 2024). "FAP expression can be increased not only in malignant lesions but also in non-cancer pathologies including fibrosis and autoimmune diseases, where the FAPi-based radiotracers uptake reflects fibrotic activity rather than inflammation." (PMID 38398230, 2024).
gastric tumour (6 papers, 2022 to 2025). "FAPI tracers, including [68Ga]Ga-FAPI-04, specifically bind to FAP and offer significantly improved tumour-to-background ratios compared to FDG in malignancies that are typically FDG-avid, such as pancreatic and gastric tumours." (PMID 40722549, 2025). "In cancer samples, a positive correlation was noted between the percentage of FAP‐positive cells and the percentage of CD31‐positive cells, suggesting that CAFs likely promote gastric tumor angiogenesis." (PMID 39764562, 2025). "After culture for 7 days, qRT-PCR and WB assays showed that the expression of POSTN, FAP, MMP2 and PDGFα in the gastric tumour cell exosome-treated group was gradually increased compared with that in the MSC control group." (PMID 37199594, 2023).
interstitial lung disease (6 papers, 2021 to 2026). A diverse group of lung diseases that affect the lung parenchyma. "Similarly, FAP imaging is used to assess extra-articular manifestations, such as interstitial lung disease and cardiac fibrosis, by mapping fibroblast activity, offering a non-invasive tool." (PMID 40607439, 2025). "Another study reported that FAP-specific PET/CT imaging in fibrotic interstitial lung diseases and lung cancer provided potential clinical value for the monitoring and therapeutic evaluation of fibrotic interstitial lung diseases and suggested that these areas be investigated in future studies." (PMID 34680237, 2021). "The expression and amount of FAPα are high in patients with both interstitial lung disease (ILD) and silicosis." (PMID 38136590, 2023). "Previous studies have identified the enrichment of immunosuppressive FAP+ fibroblasts secreting ECM and chemokines in tumors, cardiac fibrosis, and interstitial lung diseases." (PMID 39024569, 2024).
lung squamous cell carcinoma (6 papers, 2021 to 2024). "In addition, a significant survival association was found for high FAP expression with lower OS in the subpopulation of squamous cell lung cancer patients (HR 2.19, 95% CI 1.11–4.32, p = 0.02)." (PMID 35951090, 2023). "In addition, FAP contributed to shortened overall survival in subgroups of the patients with squamous cell lung cancer (p = 0.020), PD-1 blockade monotherapy (p = 0.017), and first-line therapy (p = 0.028)." (PMID 35951090, 2023). "In the subgroups of squamous cell lung cancer and non-squamous cell lung cancer, PFS was negatively related to the expression of FAP, with HRs of 2.751 and 2.323, respectively." (PMID 35951090, 2023). "A particularly strong correlation was found in squamous cell lung cancer between FAP and CD8 + T cell density, which was stronger than in the non-squamous cell lung cancer group (Spearman’s rho – 0.34, p = 0.01; Spearman’s rho – 0.30, p = 0.008, respectively)." (PMID 35951090, 2023).
multiple myeloma (6 papers, 2015 to 2026). "In multiple myeloma, FAP has been shown to activate β-catenin, leading to decreased expression of apoptotic proteins like caspase 3 and protecting tumor cells from chemotherapy-induced cell death." (PMID 41373408, 2025). "Inhibition of FAPα with PT-100 (Val-boro-Pro) influenced the expression of adhesion molecules in osteoclasts and reduced myeloma growth and bone disease." (PMID 25593080, 2015). "FAPα was upregulated in bone marrow mesenchymal stem cells and osteoclasts when co-cultured with myeloma cells and supported myeloma cell survival." (PMID 25593080, 2015). "In multiple myeloma, elevated FAP levels are correlated with poor outcomes." (PMID 41373408, 2025). "In conclusion, this study identified the mechanism that MM-BMSCs inhibit T-cell proliferation and drive Th17 differentiation through FAPα/TGF-β axis, leading to the progression of myeloma." (PMID 28881756, 2017). "MM-BMSCs inhibit T-cell proliferation and drive Th17 differentiation through FAPα/TGF-β axis, leading to the progression of myeloma." (PMID 28881756, 2017).
oral cancer (6 papers, 2019 to 2025). "In oral cancer, malignant p-EMT cells located at the invasion front are in proximity to CAFs (FAP+PDPN+) and are statistically associated with nodal metastasis and perineural invasion." (PMID 34869001, 2021). "Low expression of miR-30a-5p induces the proliferation and invasion of oral cancer by promoting the expression of FAP (Homo sapiens fibroblast activation protein α), and miR-30a-5p might be a new therapeutic target for oral cancer treatment." (PMID 31771604, 2019). "The three (FAP, FN1, and MMP1) overexpressed genes show a significant potentiality for oral cancer development." (PMID 37936719, 2023). "We chose three overexpressed genes (FAP, FN1, and MMP1) that could have potential regarding their presence in oral cancer patients." (PMID 37936719, 2023). "The oral fibroblasts we describe in this manuscript, that were activated into CAFs through oral cancer cell-derived EVs, most likely constitute the CAF-S1 subtype, positive for both CD29 and FAP, while lacking expression of CAV1." (PMID 37745296, 2023).
pancreatitis (6 papers, 2017 to 2026). Inflammation of the pancreas. "For CAFs, the mean FAP fequency was 93% (+/−SEM 1.6%), which is 5% higher than the DAFs from pancreatitis tissue, which expresses a mean of 88% FAP+ fibroblasts (+/−SEM 2.4%)." (PMID 40523922, 2025). "For visualizing the primary tumor, 18F‐FAPI‐04 avidity was observed in areas of pancreatitis adjacent to or distant from the tumor, attributed to FAP overexpression during inflammation, and at this point, contrast‐enhanced CT/MRI were taken into consideration." (PMID 40066225, 2025). "However, the uptake of 18F‐FAPI‐04 in inflammatory tissues, such as pancreatitis surrounding the tumor or distal pancreatitis, due to FAP overexpression during inflammation, may complicate the diagnosis and localization of primary tumors." (PMID 40066225, 2025). "For pancreatitis samples, 87% (+/−SEM 2.4%) were EpCAM-/FAP+; gating further results in 86% IL1R+ (+/−SEM 4.4%) and Ly6C+ (+/−SEM 4.3%) cells." (PMID 40523922, 2025). "Due to its role in tissue remodeling and expression on activated fibroblasts, FAP overexpression is also observed in several non-oncologic, fibrotic diseases including liver cirrhosis, pancreatitis, or idiopathic pulmonary fibrosis." (PMID 37345133, 2023).
prostate adenocarcinoma (6 papers, 2022 to 2025). "Our findings indicated an upregulation of FAP in nearly all examined tumor types, with a notable increase in prostate adenocarcinoma (PRAD)." (PMID 40438108, 2025). "Additionally, we used an immortalized CAF cell line with endogenous FAP expression, hPrCSC-44, and FAP-null PC-3 prostate adenocarcinoma cells." (PMID 39868181, 2025). "Additionally, we used an immortalized CAF cell line with endogenous FAP expression, hPrCSC-44, and PC3 prostate adenocarcinoma cells, which are FAP-null, but have endogenous DPPIV expression." (PMID 40804296, 2025).
renal fibrosis (6 papers, 2025 to 2026). A final common manifestation of a wide variety of chronic kidney diseases characterized by glomerulosclerosis and tubulointerstitial fibrosis. "They found that AKI was associated with renal fibrosis by day 14, and that FAP-specific PET/CT imaging was able to dynamically observe the maladaptive repair process after AKI and predict the development of renal fibrosis." (PMID 40809416, 2025). "FAP expression has also recently been demonstrated in non‐malignant pathological conditions, including wound repair, IgG4‐related disease, and renal fibrosis." (PMID 40384987, 2025). "The novel PET radiotracer 68Ga-FAPI-04 targets fibroblast activation protein (FAP), overexpressed in fibrotic tissues, and holds promise for imaging renal fibrosis, a key contributor to CKD progression and declining GFR." (PMID 41464210, 2025). "In this prospective study, 13 patients with histopathologically confirmed renal fibrosis underwent 68Ga-FAPI-04 PET/CT, with results compared to biopsy findings and immunohistochemical FAP expression." (PMID 41464210, 2025). "Fibroblast activation protein (FAP) is a membrane-anchored glycoprotein, and FAPI PET imaging has shown potential in evaluating renal fibrosis." (PMID 40028531, 2025). "Here, we show that chimeric antigen receptor-modified M2 macrophages (CAR-M2) targeting FAP and secreting interleukin (IL)-4 are delivered via an injectable HAMA-CS hydrogel beneath the renal subcapsule and attenuate renal fibrosis while promoting renal revascularization." (PMID 41887221, 2026).
squamous cell carcinoma (6 papers, 2021 to 2026). A carcinoma arising from squamous epithelial cells. "This includes FAP+ CAFs to be an indicator of positive outcome in squamous cell carcinoma and the same group also suggested in a subsequent study that this was due to high infiltration of CD8 and CD3 positive T cells in the tumours." (PMID 38582812, 2024). "JAG1 and CDCP1 were mainly highly expressed in the squamous cell carcinoma group, while FAP-α was highly expressed in the adenocarcinoma group." (PMID 35054034, 2022). "JAG1 and CDCP1 were highly expressed in patients with squamous cell carcinoma, whereas FAP-α was highly expressed in patients with adenocarcinoma in our analysis." (PMID 35054034, 2022). "In contrast to the metabolism targeted tracer FDG, FAPI reacts specifically with the surface protein FAP on CAFs which can be found in tumor stroma of many squamous cell carcinomas." (PMID 33057927, 2021).
type 2 diabetes (6 papers, 2019 to 2026). "It has been described that patients with type 2 diabetes have elevated levels of circulating FAP compared with nondiabetic subjects, thus suggesting that insulin resistance led to an inactivation of FGF21 and to the attenuation of its beneficial effects." (PMID 31546675, 2019).
urothelial bladder carcinoma (6 papers, 2021 to 2025). "An elevated FAP expression in CAFs was associated with a higher stage and poor disease-specific survival in bladder urothelial cancer." (PMID 36598731, 2023). "Higher FAP levels were found to correlate with poorer response and clinical outcomes in bladder urothelial carcinoma and cutaneous melanoma patients undergoing treatment with immune checkpoint inhibitors." (PMID 40741380, 2025). "FAP is a type II transmembrane serine protease with post proline dipeptidyl peptidase as well as endopeptidase activity and its increased expression appears to be an independent adverse prognostic factor in urothelial bladder cancer." (PMID 35349039, 2022). "They demonstrated that α-SMA, FAP, CD90, and PDGFR-α/β were involved in tumor progression in urothelial bladder cancer." (PMID 33808627, 2021). "CAF markers have been identified in urothelial bladder cancer and include α-SMA, FAP, CD90, vimentin, PDGFR-α/β, and MFAP5." (PMID 33808627, 2021). "On the contrary, CAFs promote tumorigenesis in urothelial bladder carcinoma via multiple markers, including alpha smooth muscle actin, CD90/Thy-1, platelet-derived growth factor receptor-alpha and -beta (PDGFR-α/-β) and especially in advanced stages significantly increased FAP-expression." (PMID 37763225, 2023).
colon adenocarcinoma (5 papers, 2022 to 2024). "In colon adenocarcinoma (COAD), elevated FAP accelerates malignant tumor progression by inducing resistance to immunotherapy through the reduction of immune cell infiltration levels and the promotion of an immunosuppressive microenvironment in vivo." (PMID 37490719, 2023). "We observed the highest correlation coefficients for colon adenocarcinoma (COAD), with R = 0.62 for FAP and FLT1 and R = 0.55 for FAP and KDR." (PMID 36672341, 2023).
diffuse large B-cell lymphoma (5 papers, 2020 to 2025). "However, FAP expression was found to be positively associated with improved prognosis in lymphoid neoplasm diffuse large B-cell lymphoma (DLBC, HR = 0.63, p-value = 0.00092)." (PMID 37490719, 2023). "We found that FAP expression was significantly higher in lymphoid neoplasm diffuse large B-cell lymphoma (DLBC) compared with the normal control." (PMID 37166418, 2023). "Interestingly, measuring intratumoral FAP levels revealed an inverse pattern, with diffuse large B-cell lymphoma showing higher tissue FAP localization compared with follicular lymphoma (p < 0.001)." (PMID 41373408, 2025).
esophageal squamous cell carcinoma (5 papers, 2017 to 2025). Esophageal squamous cell carcinoma (ESCC) is a type of esophageal carcinoma (EC) that can affect any part of the esophagus, but is usually located in the upper or middle third. "Low circulating FAP concentrations were associated with higher tumor stage in patients with esophageal squamous cell carcinoma." (PMID 40690098, 2025). "In a clinical investigation, stromal FAP expression was evident in most Esophageal Squamous Cell Carcinoma (ESCC) samples but was absent in adjacent normal tissue." (PMID 37316886, 2023).
Familial adenomatous polyposis (5 papers, 2015 to 2024). Familial adenomatous polyposis (FAP) is characterized by the development of hundreds to thousands of adenomas in the rectum and colon during the second decade of life. "On the same day, a craniocerebral MRI scan and a blood draw for the familial adenomatous polyposis FAP test were conducted." (PMID 37864148, 2023).
familial amyloid polyneuropathy (5 papers, 2016 to 2022). "The FAP‐RODS only explores limitations in physical and social activities, and was developed in Portugal in a population including only subjects with V30 M familial amyloid polyneuropathy; therefore, it might not perform well in patients with other mutations or other amyloid types." (PMID 33982288, 2021).